IFNG (interferon gamma)
Diseases named in the same sentence as IFNG in open-access papers (continued):
Sharing a sentence is not in itself a finding about the gene and the disease.
tumor (continued). "For example, interferon gamma (IFNγ) is an anti-tumor cytokine released by activated T and NK cells." (PMID 33379189, 2020). "Studies have demonstrated that IFNγ not only impedes tumor growth by acting directly on cancer cells, it also acts on the tumor stroma and tumor angiogenesis for effective rejection of large, established tumors." (PMID 32559853, 2020). "IFNγ affects tumor cell immunogenicity directly and is of critical significance in promoting tumor cell recognition and elimination." (PMID 32902917, 2020). "Genetic ablation of other complement proteins such as C3 was also shown to have profound inhibitory effects on primary tumor growth and metastasis correlating to increased numbers of IFNγ+/TNFα+/IL10+ CD4+ and CD8+ T-cells." (PMID 33718121, 2020). "When stimulated with α-GalCer or its analogs, NKT cells rapidly produce pro- and anti-inflammatory cytokines including IFNγ, TNFα, IL-10, IL-4, IL-13, IL-17 and GM-CSF, and participate in the regulation of infection, autoimmunity, and tumor immunity." (PMID 32153574, 2020). "Exposure to increased IFNγ mediates tumor upregulation of PD-L1 as a way to shut down immune responses." (PMID 32499782, 2020). "Concurrently, we also observed increased levels of IFNγ, as measured through a multi-cytokine panel of bulk tumor." (PMID 33247183, 2020). "Testing for IFNγ secretion after over-night incubation at a T cell/target ratio of 1:1 revealed γδCAR-T cells are highly reactive against CD19 expressing tumor cells." (PMID 32714329, 2020). "In WT mice, combination therapy required CD8+ cells and IFNγ signals for efficacy, and increased the expression of multiple effector molecules by anti-tumor CD8+ TILs." (PMID 32917858, 2020). "Two different strategies have been developed to reduce systemic toxicity of TNF or IFNγ while preserving their anti‐tumor activity." (PMID 31916677, 2020). "The immune cell subpopulation infiltrated into the tumor mass as well as the expression of interferon-gamma (IFN-γ) and tumor necrosis factor-alpha (TNF-α) in T cells was assessed by flow cytometry and/or immunohistochemistry." (PMID 33020243, 2020). "As a result, the activated CD4+ T cells promote antitumor immune responses by secreting IFNγ that triggers macrophages and NKs, blocks angiogenesis, regulates the tumor stroma formation, and leads to direct tumor cell lysis." (PMID 33228747, 2020). "Inflammatory cytokines such as interferon-gamma induce PD-L1 expression, both in tumour cells and in myeloid-derived cells infiltrating the tumour microenvironment." (PMID 33233705, 2020). "These activated T cells in turn secrete more IFNγ to stimulate tumor cells, and upregulate checkpoint pathways on T cells and tumors cells as well." (PMID 32358509, 2020). "Of note, also CD4+ T helper cells in our tumor model showed reduced functionality as reflected by reduced production of IFNγ." (PMID 33344239, 2020). "On the other hand, chronic tumor-cell exposure to IFNγ—secreted by Type 1 ILCs, among others—has been proposed as a relevant regulator of immune checkpoints." (PMID 33138017, 2020). "Upon exposure to IFNγ, tumor cells will develop adaptive immune resistance against the immune attack via expression of various ligands for immune checkpoints." (PMID 33050520, 2020). "Similar tumor inhibition and mortality were found in a subsequent publication which also correlated high plasma levels of IFNγ and TNFα with toxicity." (PMID 33178203, 2020). "The IFNγ pathway also enables the recruitment of immune cells and has direct anti-proliferative and pro-apoptotic effects on tumor cells." (PMID 35582435, 2020). "Pre-treatment with poly(I:C), IFNγ and anti-IL-10 increased NK infiltration and sensitized four different tumor models to subsequent ICB." (PMID 32133005, 2020). "In general, CAR-T cells would kill tumor cells accompanied with the release of cytokines, including IL-2, IL-4, IL-6, IFNγ, and TNFα." (PMID 31998790, 2020).
tumor (continued). "When tumor cells are infiltrated by cytotoxic T lymphocytes (CTLs), the PD-L1 expression will be induced by IFNγ secreted from CTLs in preparation for an immune attack." (PMID 33519429, 2020). "This was reliant on PTPN2 deficiency driving the IFNγ‐induced and STAT‐1‐mediated expression of antigen‐presentation pathway genes and T‐cell chemoattractants, such as Cxcl9 in tumour cells." (PMID 31803974, 2020). "We observed a 5–7- fold increase in the frequency of tumor antigen specific CD8 T cells expressing IFNγ and TNFα in FOLFOX-treated tumors compared to controls." (PMID 32391270, 2020). "AZD6738 increased cell proliferation, infiltration, and interferon-gamma (IFN-γ) production of tumor-infiltrating lymphocyte CD8+ T cells, resulting in decreased T cells and tumor-infiltrating lymphocyte Tregs in mice xenografts." (PMID 32883316, 2020). "Beyond oxidative stress, myeloid cells are a crucial source of inflammatory cytokines, which can support the survival and proliferation of neoplastic cells (e.g., IL-6, IL-1, IL-23, IL-17A) or the activation of adaptive anti-tumor immunity (e.g., IL-12, IFNγ)." (PMID 32962159, 2020). "Analysis of IFNγ secretion by either CD4 or CD8 T cells showed increased production with only RX-5902 treatment alone in tumor tissue." (PMID 33148223, 2020). "The involvement of noncHLAIp in tumor immune recognition was assessed by measuring IFNγ release upon peptide stimulation of autologous tumor-infiltrating lymphocytes (TILs) or peripheral blood mononuclear cells (PBMCs) from the same patient." (PMID 32157095, 2020). "Genetic alterations that cause cell transformation generate neoantigens for immune recognition, leading to T lymphocyte activation, which can prevent tumor outgrowth, through cytotoxic activity and interferon-gamma (IFN-γ) signaling." (PMID 33335860, 2020). "T cells primed with DC pulsed with SJPDGF1-APOBEC3BACTIVE-modified lysate secreted increased levels of IFNγ compared to irrelevant (Mel888) or unmodified (SJPDGF1) tumor lysates, which further increased in the presence of anti-PD1 antibodies." (PMID 32034147, 2020). "Trajectories of tumor growth, IFNγ and ratio of TE3 to TR arising from the model are extremely close to corresponding data from the experiments." (PMID 31914948, 2020). "Reactive T cells isolated from A7450 T1 M1-treated mice recognized autologous Mlh1−/− tumor cells in IFNγ ELISpot, but likewise YAC-1 cells, indicative for stimulation of both arms of the immune system." (PMID 33087163, 2020). "Encouragingly, results also showed increased IFNγ release from splenocytes after tumor stimulation, suggesting that D24-RGD stimulated a systemic immune response to reduce tumor burden and improve overall survival." (PMID 32155969, 2020). "We found that YAP was tightly linked to IFNγ response in CD8 T cells, especially in activated cytotoxic cells usually found in the tumor microenvironment." (PMID 32322254, 2020). "Our work shows that a substantial fraction of tumor-specific CTLs have a compromised IFNγ response and a hypermethylated IFNγ promoter, especially at the CpG positions within the transcription factor binding sites." (PMID 32194559, 2020). "In human gastric cancer, tumor infiltrating monoctyes/macrophages can reduce IFNγ, TNFα, and Ki-67 expression of NK cells via TGFβ1, thus impairing NK cell function." (PMID 32762681, 2020). "Together, these results suggest that increased IFNγ production by CD8+ T cells contributes to the anti-tumor activity of anti-GARP:TGF-β1 combined with anti-PD-1." (PMID 32917858, 2020). "After 5 days, tumor cell lysis was calculated based on decreased confluency of tumor cells in the cell culture images and the supernatant was collected to assess IFNγ production by ELISA." (PMID 32642679, 2020). "Vice versa, immune cells such as CD8+ T-cells in highly inflamed tumors were found to mediate induction of IDO in tumor cells via IFNγ signaling." (PMID 33072086, 2020).
tumor (continued). "Tumor IFNγ expression has been identified to be closely correlated with favorable clinical outcome for multiple cancer types." (PMID 32902917, 2020). "We recently identified that intratumoral PD-1+Lag3+Tox+ exhausted tumor antigen-specific T cells not only lose functionality (e.g., IFNγ, TNFα), they progressively express IL-10 specifically in the TME." (PMID 33584701, 2020). "miR-155 expression in T cells seems to limit tumor growth, and promote IFNγ production by T cells within the tumor microenvironment." (PMID 32206186, 2020). "NK cells can promote the expression of PD-L1 in tumor cells through secretion of IFNγ, which generates an immunosuppressive tumor microenvironment that impedes NK cell activity." (PMID 33120910, 2020). "We observed that tumor cell lysis is positively correlated with IFNγ production, indicating that intratumoral T cells retain their capacity to perform cytotoxic effector functions ex vivo (<.01)." (PMID 32642679, 2020). "Functionality assays confirmed a significant positive correlation between tumor cell lysis and IFNγ production in ex vivo cultures (Spearman r = 0.9524; P < .01)." (PMID 32642679, 2020). "As the tumor site is additionally an important interaction site for CTLs and MDSCs, we assessed frozen tumor sections for CD8a and IFNγ by immunoflourescent staining." (PMID 32106810, 2020). "The innate and adaptive antitumor response to the abnormal cellular growth begins with the production of interferon gamma by activated T cells, natural killer (NK) cells, and the tumor microenvironment." (PMID 33114616, 2020). "Consistently, the ablation of p50, as well as pharmacological inhibition of EP2 by AH6809, has reprogrammed M-MDSC towards a NOS2low/TNFαhigh phenotype, restoring the in vivo anti-tumor activity of IFNγ." (PMID 32962159, 2020). "The presence and activation status of dendritic cells (DCs) and CD8+ T cells and anti-tumor cytokines such as IFNγ determine the responsiveness to RT." (PMID 33050580, 2020). "The upregulation of tumor PD-L1 in response to IFNγ from CD8 T cells is an adaptive immune resistance mechanism that similarly occurs in response to FOLFOX- and Xeloda-based chemotherapy." (PMID 32079180, 2020). "A lack of CCR2 expression on HSPCs reduces splenic myelopoiesis, impairs the suppression activity of tumor MDSCs, allows an increase in the number of tumor-infiltrating IFNγ+CD3+CD8+ CTLs, and enhances immunotherapy efficacy." (PMID 32582203, 2020). "This is particularly relevant in the NK cell context given that interferon gamma production is one of the main ways that NK cells contribute to inflammation and cytotoxicity in the tumor microenvironment." (PMID 32040476, 2020). "Tumor endothelial cell expression of IDO1 was positively correlated with T-cell infiltration and IFNγ expression in the tumor." (PMID 32231867, 2020). "IFNγ reprograms TAMs into a tumoricidal (M1) phenotype, and promotes anti-tumor T-cell responses, inducing tumor-specific T cell memory, facilitating the differentiation of Th1 cells, and inhibiting the expression of exhaustion marker PD-1 on CD8+T cells." (PMID 32397392, 2020). "As a soluble dimeric cytokine in charge of tumor immune surveillance and cytotoxicity, IFNγ endows macrophages polarized toward an M1 state of enhancing pro-inflammatory reaction and resisting to immune tolerance." (PMID 33505964, 2020). "While PDL1 is expressed by tumor cells and immune cells, IFNγ is primarily expressed by T cells as well as NK cells, and characterized as an anti-proliferative agent." (PMID 32668709, 2020). "On the other hand, studies also demonstrated that IFNγ not only impedes tumor growth by acting directly on cancer cells, it also acts on the tumor stroma and tumor angiogenesis for effective rejection of large, established tumors." (PMID 32559853, 2020).
tumor (continued). "Collectively, we found that M2 polarized BMMs (IL-4-induced, or tumor conditioned media induced) had increased expression of Myc mRNA as compared to M0 or IFNγ-induced M1 macrophages." (PMID 32685002, 2020). "The increase in IDO1 in B16-F10 tumor endothelial cells treated with agonistic CD40 mAb correlated with IFNγ expression in the tumor tissue." (PMID 32231867, 2020). "Specific blockade of IFNγ signaling in tumor cells resulted in increased sensitivity to PD-1 blockade in an NK/ILC1-dependent manner." (PMID 32133005, 2020). "To validate the CD4/CD8 T‐cell enhanced effector function, as suggested by the in silico analysis, we analysed the expression of IFNγ, perforin and granzyme b in the tumour‐infiltrating lymphocyte populations by flow cytometry." (PMID 32567735, 2020). "The intracellular uptake of cytosine-phosphate-guanine (CpG) promoted the infiltration of cytotoxic T lymphocytes (CTLs) in tumor tissue, further stimulating the production of interferon gamma (IFN-γ) and remarkably elevating the immune response level." (PMID 32620811, 2020). "In the same line, it was reported that ex vivo expanded and antibody-activated NK cells that were adoptively transferred to patients exhibited potent IFNγ secretion and significant anti-tumor activity against pancreatic cancer cells." (PMID 33022971, 2020). "Concomitant blockade of both molecules (CTX + anti-PDL1/2) further increased the number of tumor-specific CD8+ T cells producing IFNγ." (PMID 32290265, 2020). "Type I interferons (e.g., interferon alpha) stimulate activity of dendritic cells and priming of lymphocytes T, while type II interferons (interferon gamma) affect both immune cells and tumor cells and facilitate elimination of the latter ones." (PMID 32517213, 2020). "In particular, treatment with anti-CTLA-4 and anti-PD-1 therapy in the low tumor burden state can lead to IFNγ dependent activation induced cell death of T cells." (PMID 32581235, 2020). "In preclinical studies, a single intratumoral injection of mRNA encoding murine IL-12 (mIL-12) increased IFNγ expression and genes associated with a Th1 response in MC38 tumor-bearing mice." (PMID 33178203, 2020). "Using a B16 cell line that progressed after ICB, they found that resistance was due to enhanced IFNγ/PD-L1 signaling in the tumor cells." (PMID 32133005, 2020). "We have shown, for the first time to our knowledge, that human tumor-specific CTLs can be dysregulated by hypermethylation of the IFNγ promoter, which compromises transcription and, in turn, the protein synthesis of IFNγ." (PMID 32194559, 2020). "Here, we show that tumor-specific CTL clones have impaired IFNγ expression and production upon activation." (PMID 32194559, 2020). "In cancer patients a tumor response involving CD8+ T cells, TH1 CD4+ T cells, and IFNγ producing natural killer cells is associated with a better prognosis." (PMID 33344239, 2020). "Although IFNγ displays complex immunoregulatory characteristics that include induction of potentially tumour‐supporting IL‐18 binding protein, its tumour‐suppressive properties apparently override in the context HCC." (PMID 32697038, 2020). "In fact, the anti‐tumor effects of TNF and IFNγ on activated tumor vasculature are probably the reason why immunotherapy using T cells can destroy solid tumors that are refractory to cytotoxic therapies." (PMID 31916677, 2020). "This PD-L1 secretion can be significantly amplified in tumor cells and in exosomes in response to interferon gamma (IFN-γ)." (PMID 33396739, 2020). "Cluster 1 had the lowest cytotoxic activity, tumour‐infiltrating lymphocytes and interferon‐gamma (IFN‐γ), as well as immune checkpoint molecules expressions." (PMID 33184998, 2020). "An IDO1/AhR inhibitor reversed the tumor dormancy response and resulted in reduced spheroid growth after exposure to IFNγ in vitro." (PMID 33379189, 2020).
tumor (continued). "The binding of TIM-3 by galectin-9, a soluble s-type lectin, triggers an exhausted phenotype characterized by low proliferation and secretion of IL2 and IFNγ in tumor infiltrating CD4+ and CD8+ cells." (PMID 32937953, 2020). "Treg infiltration of the tumor site decreased by ~25%, concomitant with a 50% increase in IFNγ expression within the CD8+-positive population." (PMID 31911617, 2020). "How a large fraction of tumor-specific CTLs acquire hypermethylation of the IFNγ promoter merits further investigation." (PMID 32194559, 2020). "The upregulation of HLA class I genes is important for tumor immune surveillance by IFNG treatment in PMF." (PMID 32331228, 2020). "In human monocytes, IL-27 also upregulates HLA-E, which, upon interacting with CD94/NKG2A, suppresses the NK cell functions and IFNγ release which, in turn, weakens the anti-tumor immunity." (PMID 32143355, 2020). "Second, we administered a neutralizing anti-IFNγ mAb into tumor-bearing mice on the same days as treatments with anti-GARP:TGF-β1 and anti-PD-1." (PMID 32917858, 2020). "The treatment also increases tumor-infiltrating IFNγ-producing CD4+ and CD8+ T cells and inhibits tumor growth in vivo." (PMID 33086676, 2020). "Interferon gamma (IFN-γ) and IL-6 are two important cytokines associated with immune responses against tumor cells." (PMID 32375828, 2020). "It was postulated that TNFα upregulates expression of IFNγ receptors trough the NF-κB pathway resulting in enhanced IFNγ signaling in HCC cells thereby promoting tumor growth." (PMID 32486375, 2020). "This notion is supported by the increased frequencies of CD4+ effector cells (Th1, Th2, and Th17) and CD8+ effector cells in TDLNs, the unique kinetics of plasma IFNγ levels, and the impaired accumulation of T cells, B cells and NK cells in the lung and tumor." (PMID 32770025, 2020). "Our study however, showed that IFNγ expression increased in the ablative group following the increase in infiltration of CD8+ cells into the tumor region after high-dose exposure." (PMID 32287292, 2020). "Further analyses of T-cell subsets revealed that while there was no change in T-regulatory cells, a significant increase in the number of tumor infiltrating interferon gamma (IFNγ) producing CD8+ effector T cells was noted." (PMID 32198351, 2020). "The expression of CD107a and IFNγ by Vγ9Vδ2 T cells after co-cultures with the different tumor cell lines was measured by flow cytometry." (PMID 32733462, 2020). "Consistent with an increased Th1 response, a trending increase in CD4+/IFNγ+ T cells and a significant increase in CD8+/IFNγ+ T cells per milligram tumor weight were observed in bintrafusp alfa-treated animals compared to controls." (PMID 32373533, 2020). "Similar results were seen with both tumor models in WT mice where either IFNγ or IL-17A significantly decreased tumor size." (PMID 33042110, 2020). "Further, changes in IFNγ and PD-L1 expression indicate that the combination therapy is highly effective in generating an anti-tumor response." (PMID 33584714, 2020). "Blocking RAGE results in inability of TNFα, TNFα/IFNγ, and tumour‐CM to activate the signalling pathways leading to muscle protein degradation." (PMID 32159297, 2020). "These Th1 cells produce the pro-inflammatory cytokines interferon gamma (IFNγ) which promotes bactericidal activity, secretion of other pro-inflammatory cytokines, and tumor suppression by macrophages." (PMID 32373130, 2020). "Although IFNγ is known to support anti-tumor immunity, we further showed that it is sufficient to shrink tumors in both colon and pancreas." (PMID 33042110, 2020). "The authors also found that LPA induced intracellular Ca2+ mobilization and increased interferon gamma (IFNγ) secretion in activated NK cells, a proinflammatory cytokine critical for viral and tumor eradication." (PMID 32397679, 2020).